MIR1184-3 (microRNA 1184-3)
Synonyms: hsa-mir-1184-3
Gene: MicroRNA gene on chromosome X (155,457,517 to 155,457,615, forward strand). Ensembl gene ENSG00000221603.
Homologues: Orthologues: chimpanzee ptr-mir-1184-1 (100% identical). Paralogues in human: MIR1184-1 (100% identical), MIR1184-2 (100% identical).